ALDH1A1 (aldehyde dehydrogenase 1 family member A1)
Diseases named in the same sentence as ALDH1A1 in open-access papers (continued):
Sharing a sentence is not in itself a finding about the gene and the disease.
cancer (continued). "This analysis revealed a significant positive correlation of ALDH1A1 with several gene sets related to cancer progression, e.g. WNT signaling, angiogenesis, osteogenesis, extracellular matrix and adhesion molecules." (PMID 38169509, 2024). "Prior experimental results have demonstrated that Aldh1a1, as a crucial upstream molecule of Zbtb7b, contributes to the immune evasion of cancer cells." (PMID 39107297, 2024). "Our data support that ALDH1A1, which has already been proposed as a prognostic maker for early invasiveness of cancer, is clearly upregulated in regions of high dysplasia." (PMID 39252972, 2024). "ALDH1A1 overexpression has been observed in various cancers, including breast, colon, esophageal, liver, ovarian, pancreatic, and gastric, and the effect on disease prognosis varies between cancer types." (PMID 38928275, 2024). "Gene Set Enrichment Analysis (GSEA) 17 confirmed that genes downregulated after the knockdown of both ALDH1A1 and ALDH1A3 were enriched in the datasets associated with normal stem cells, tumor progenitors and poorly differentiated cancer." (PMID 38169509, 2024). "In this study, we examined the expression of the pluripotency genes (NANOG, SOX2, and POU5F1) and the ALDH1A1 gene in ER+ BC tumors across three large cancer datasets." (PMID 38400679, 2024). "A pivotal function of ALDH1A1 includes the conversion of retinol to retinoic acids, driving cancer proliferation through multifaceted mechanisms." (PMID 39394200, 2024). "Through preliminary detection of clinical patient tissues, we have found that ALDH1A1 was a key gene for the prognosis of cancer patients and tumor glycolysis." (PMID 39107297, 2024). "In the present study, we sought to demonstrate the pro-tumor effect of ALDH1A1 by examining the Akt/mTOR signaling pathway, thereby demonstrating the potential feasibility of targeting ALDH1A1 for cancer therapy." (PMID 39107297, 2024). "Materials & Methods: In the present study, ALDH1A1 expressing oral (OCSCs) and breast (BCSCs) cancer stem cells were sorted and used to investigate the role of sulfasalazine to induce ferroptosis." (PMID 39513121, 2024). "These experiments aimed to evaluate the presence and activity of ALDH1A1 in these specific cancer cell lines." (PMID 38495994, 2024). "This resistance mechanism is partly due to the ability of ALDH1A1 to detoxify aldehydes generated by chemotherapy, thereby protecting cancer cells from cytotoxicity." (PMID 39534872, 2024). "In conclusion, we examined the associations of several reproductive variables with the expression of stem cell markers CD44, CD24, and ALDH1A1 in cancer-free women." (PMID 38577336, 2024). "As a consequence, stabilized OCT1 contributed to ALDH1A1 upregulation and enhanced cancer stemness, implying the therapeutic potential of targeting serial ubiquitination in patients with CRC." (PMID 37298124, 2023). "The PPI networks and survival analysis identified two important genes, ALDH1A1 and CFD, that are strongly associated with the progression of tumors and cancer." (PMID 37359050, 2023). "ALDH1A1 is considered a universal cancer stem cell marker and already serves as a therapeutic target for different selective inhibitors due to its role in chemoresistance." (PMID 36768723, 2023). "In tumour tissues, ALDH1A1 was highly expressed in secretory-type cancer epithelial cells and neuroendocrine tumour cells." (PMID 36651035, 2023). "Positive staining for ALDH1A1, in most cases, was visible in individual or small groups of cancer cells." (PMID 36768723, 2023). "They demonstrated the effects of ALDH1A1 in generating a microenvironment that promotes the progression of cancer via NFκB." (PMID 37298333, 2023).
cancer (continued). "Recently, isoform‐specific inhibitors are under investigation in cancer research, and some inhibitors can target ALDH1A1, ALDH2, and ALDH3A1." (PMID 36694633, 2023). "Human sarcoma cell line subclones, xenografts, and patient specimens that were selected for resistance to sorafenib had cancer stem cell properties, increased aldehyde dehydrogenase activity, and staining for ALDH1A1." (PMID 37298333, 2023). "Surviving cancer cells that managed to escape the cytotoxic effects of GEM or 5‐FU were investigated for the expression of four CSC markers: ALDH1A1, PON1, CD44, and EpCAM." (PMID 36400567, 2023). "High aldehyde dehydrogenase activity has been considered a marker of cancer stem cells, and ALDH1A1 has been suggested as a target for immunological therapeutics of many types of cancer." (PMID 37893215, 2023). "Increased expression and activity of aldehyde dehydrogenase 1A1 (ALDH1A1) have been reported as robust cancer stem cell markers." (PMID 37726723, 2023). "In several solid cancers, high expression and activity of ALDH1A1 are considered to be closely related to the stemness phenotype and to contribute to cancer progression, as well as being a biomarker for poor prognosis and low survival." (PMID 36400567, 2023). "ALDH1A1 overexpression in bladder cancer patients activates the retinoic acid signaling mechanism, thus elevating cancer progression." (PMID 37645246, 2023). "This suggests that the role of ALDH1A1 can become redundant for cancer cells under certain conditions, while it can support essential physiological functions and thereby benefit the host organism." (PMID 37298333, 2023). "Then, we evaluated the expression of c-Myc, CD44, CD24, CD133, and ALDH1A1 of sixty primary cancers and paired lymph nodes with cancer evasion." (PMID 37353799, 2023). "ALDH1A1 has also been shown to exhibit metabolic activity and contribute to the promotion of DNA repair, thereby affecting cancer progression." (PMID 37954205, 2023). "In general, for cancer stem cells ALDH1A1 was proposed as a reporter & marker for self-renewal (clonogenicity), chemoresistance, invasiveness, and metastasis." (PMID 37298333, 2023). "It has also been demonstrated that ALDH1A1 binds to and diminishes the effectiveness of cytotoxic drugs such as flavopiridol and some cancer medications that target topoisomerase, such as daunorubicin." (PMID 37686694, 2023). "ALDH1A1 is involved in cancer stem cell maintenance, metabolism, and drug resistance in multiple cancer types, including melanoma." (PMID 36831600, 2023). "EBA induces apoptosis in BCSC-like populations, as evidenced by a significant increase in cleaved caspase-3 and PARP degradation as well as downregulation of the cancer stem cell markers ALDH1A1, CD49f, Nanog and Sox2 in BCSC-enriched mammospheres." (PMID 37185776, 2023). "Metabolic enzymes AKR1B10, ALDH3A1, and ALDH1A1 have been reported by our group and others as leading candidate biomarkers for multiple cancer types, including lung." (PMID 37760474, 2023). "Even so, our work provides additional evidence supporting the consideration of PPP enzymes and ALDH1A1 as potential therapeutic targets for various cancers." (PMID 37893215, 2023). "The knockdown of PFKFB3 inhibits the expression of cancer stemness markers such as CD133, ALDH1A1, CD44, Sox2, and ABCG2, which are also associated with chemotherapy resistance." (PMID 37919747, 2023). "Given that ALDH1A1 is frequently elevated in multiple cancer and contributes to cancer cell proliferation and chemoresistance via multiple mechanisms, specific inhibition of ALDH1A1 activity is considered a promising strategy for the cancer treatment." (PMID 37429899, 2023). "ALDH1A1 is a robust marker for CSCs in ovarian and other cancers, and ALDH1A1 expression in patient tumors predicts poor prognosis." (PMID 35884498, 2022). "This approach provided greater insights into the pathways through which ALDH1A1 drives the development of cancers." (PMID 35814382, 2022).
cancer (continued). "ALDH1a1 inhibitors are promising therapeutic agents for various disorders, including metabolic disorders, cancer, and inflammation." (PMID 35056791, 2022). "Aldh1a1 is a marker for a cancer stem cell or tumour initiator phenotype and it is possible that elevated Aldh1a1 expression is a sign that Dkk-1 has the capacity to induce this in all or a subset of MOSJ-Dkk-1 cells." (PMID 35277659, 2022). "TP73-AS1 promotes TMZ resistance in GBM CSC and is linked to regulation of the expression of metabolism-related genes and ALDH1A1, a protein known to be expressed in cancer stem cell markers and which protects GBM CSC from TMZ treatment." (PMID 34996478, 2022). "Our review described comprehensively the mechanisms of ALDH1A1 in the different processes of cancers and ALDH1A1 expression regulation." (PMID 35814382, 2022). "For down-regulated genes by TRPs, ALDH1A1 modulates the activity of lysosomal autophagy inhibitors in cancer cells." (PMID 36072430, 2022). "Among the most common cancer stem cell markers, only ALDH1A1 overexpression significantly affected the five-year OS of primary head and neck squamous cell carcinoma patients." (PMID 35814382, 2022). "Because the retinoic acid (RA) signaling pathway is involved in the regulation of gene expression in cancer stem cells (CSCs), researchers have focused on the role of ALDH1A1 in cancers worldwide." (PMID 35814382, 2022). "After that, we detected the mRNA levels of OCT4 and ALDH1A1, cancer stemness markers of RCC cells that were also proved to be regulated by Wnt/β-catenin signal activity." (PMID 36319622, 2022). "As a metabolic enzyme, the effect of ALDH1A1 on metabolism plays an important role in cancer progression." (PMID 35814382, 2022). "In conclusion, ALDH1A1 is a promising cancer stem cell marker and a significant predictor of progression and poor survival." (PMID 36120232, 2022). "This review will provide insight into the status of ALDH1A1 research and new viewpoint for cancer therapy." (PMID 35814382, 2022). "Currently, ALDH1A1-targeted therapy is widely used in cancer treatment, but the mechanism by which ALDH1A1 regulates cancer development is not fully understood." (PMID 35814382, 2022). "For example, BOP1 overexpression confers chemoresistance on TNBC cells via stimulating the WNT signaling and cancer stem cell phenotypes, such as aldehyde dehydrogenase 1A1 (ALDH1A1)." (PMID 36497066, 2022). "Some of them believe that the combination of anti-ALDH1A1 therapy and chemotherapy can offset the ALDH1A1-induced drug resistance in cancer patients." (PMID 35814382, 2022). "Because ALDH1A1 is an oncogenic factor in many cancers, treatments targeting ALDH1A1 have become a research hotspot." (PMID 35814382, 2022). "Overexpression of ALDH1A1 in MKN-28, a GC cell line, by the recombinant plasmid, pEGFP-N1-ALDH1A1, can increase the proliferation, colony formation, and invasion ability of cancer cells." (PMID 35310914, 2022). "Among the inhibitors tested, the KS100 compound showed to be the most potent against ALDH1A1, 2, and 3A1, displaying anti-proliferative activity and increasing ROS levels and lipid peroxidation in several in vitro cancer models." (PMID 35299840, 2022). "We next examined the cancer stemness level of the examined cell lines to help interpret experimental observations using ALDH1A1, a canonical marker of cancer stemness, as the molecular index." (PMID 35860596, 2022). "ALDH1A1 positivity, respectively, ranged from 43.2% to 89.4% and 10%–43.4% in cancer tissue and in para-cancer tissues." (PMID 35310914, 2022). "To understand the roles of ALDH1A1 in cancers, we reviewed and summarized representative correlative studies in this article." (PMID 35814382, 2022). "Taken together, our findings demonstrated that SOX9 silencing markedly reduced the expression and activity of cancer stem cell marker ALDH1A1 and inhibited cancer cell migration." (PMID 35159173, 2022).
cancer (continued). "Although ALDH1A1 is seen as an oncogenic factor, it also exhibits different characteristics in some cancers." (PMID 35814382, 2022). "Higher ALDH1A1 expression was observed in PD-L1+/HTIL tumors in comparison to PD-L1−/LTIL carcinomas (85% vs. 37.1%; p = 0.001)." (PMID 36139578, 2022). "Meta-analysis results found that lower ALDH1A1 and ALDH1L1 expression was associated with poorer overall survival and poorer progression-free survival in cancer patients." (PMID 34680942, 2021). "Mechanistic investigations identified through the NFATc2/SOX2/ALDH1A1 axis, oxidative stress induced by cancer drug treatment is attenuated, leading to increased resistance in a mutation-independent manner." (PMID 34187410, 2021). "High expression and activity of ALDH1A1 is a characteristic feature of stem cells of normal tissues and cancer stem cells and this property has been exploited for the isolation of stem cells." (PMID 33495566, 2021). "Inhibition of ALDH1A1 by ALDH inhibitors and silenced ALDH1A1 expression by shRNA lentiviral transfer suppressed proliferation and spheroid formation of cancer cells from long-term BC patients." (PMID 33805295, 2021). "Following RARβ silencing, the down-regulation of cancer-related genes, ALDH1A1, CYP24A1, BIRC5, EDN1, IL-1β and PTGS2 in A549 parental cell suggest the importance of RARβ in controlling the expression of genes related to carcinogenicity." (PMID 33995625, 2021). "Montelukast also significantly decreased amounts of cancer-stem cells, as well as macrophage infiltration and decreased expression of ALDH1A1, DCLK1 and BCL2 in the tumor tissue." (PMID 35008546, 2021). "As demonstrated in the top DEGs, specifically cancer stem lineage clusters expressed high levels of stemness feature genes including ALDH1A1, PROM1, and NES, while ductal lineage cluster expressed high levels of ductal markers such as MMP7, TSPAN8, and SOX9." (PMID 34732701, 2021). "ALDH1A1 is a marker for cancer stem cells, can be a therapeutic target in cancer, and is involved in cyclophosphamide resistance." (PMID 33452395, 2021). "As ALDH1A1 is a CSC marker for a wide variety of cancers, reporter constructs for CSCs based on ALDH1A1 promoter have been generated." (PMID 34150761, 2021). "The expression of ALDH isoform 1A1 (ALDH1A1) is considered the universal marker of cancer cells among solid tumors." (PMID 33921897, 2021). "ATRA used in combination with gefitinib in cancer stem-cell-like adenocarcinoma decreased CSC-mediated resistance by reducing ALDH1A1 and CD44 expression and increasing the anticancer effects of gefitinib in NSCLC/ADC." (PMID 33477367, 2021). "Aldheide Dehydrogenase 1 family, A1 (ALDH1A1), is a detoxification enzyme, which has been reported to be responsible for chemoresistance in cancer." (PMID 33503899, 2021). "ALDH1A1 is a marker for normal and cancer stem cells of various tissue types, including a healthy and a cancerous prostate." (PMID 34572930, 2021). "The expression levels of cancer stem cell marker proteins ALDH1A1, C‐Myc, OCT4, NANOG, KLF 4 and SOX2 were found to be significantly higher in MCF‐7‐CSC than those in MCF‐7." (PMID 33305893, 2021). "Some of the specific transcripts observed included those from the well-established cancer survival genes ALDH1A1, SURVIVIN, XIAP, HSPG2, BCL9, and SOX4." (PMID 34579762, 2021). "The significance of ALDHHi population expressing ALDH1A1 at the single-cell level was investigated in the cancer context also." (PMID 34150761, 2021). "Previously, aldehyde dehydrogenase 1A1 (ALDH1A1) was reported as a cancer stem cell marker and suggested to have a favourable prognostic role for cervical cancer." (PMID 34099718, 2021). "A combination of ALDH1A1 inhibition with the conventional treatment is a promising strategy for developing more efficient cancer therapies." (PMID 34572930, 2021).
cancer (continued). "Associations between ALDH1A1 expression and immune subtypes across human cancers were included for analysis, and ALDH1A1 expression dominated in all the subtypes, participating in multiple immune reaction processes." (PMID 34545132, 2021). "The efficacy of these analogs in cancer cell in vitro models has been characterized and further comparison between the developed ALDH1A1 inhibitors and disulfiram is needed." (PMID 32575908, 2020). "We then analyzed by RT-qPCR the expression of the different markers involved in the cancer stem cells’ biology (Sox2, Oct3/4, Notch1, Nanog, Abcg2, Aldh1a1 and Aldh1a3)." (PMID 32610610, 2020). "This review discusses the involvement of ALDH1A1 in the development of different hallmarks of cancer to propose it as a novel putative target for cancer treatment to achieve better outcome." (PMID 35582039, 2020). "Our results provide insight into the consequence of CSN6–TRIM21 signalling on OCT1/ALDH1A1 expression during carcinogenesis and cancer progression." (PMID 32225170, 2020). "WB results showed that the expression of the cancer stem cell markers ALDH1A1, CD44, and Nanog was upregulated when cells were stimulated with LY CM, but this upregulation was diminished when cells were treated with LY + Met CM." (PMID 33116117, 2020). "Aldehyde dehydrogenase 1 family, member A1 (ALDH1A1) was used as a marker to isolate BCSCs from two established cancer cell lines, 5637 and UM-UC-3, by flow cytometry, and RNA m6A methylation abundance was evaluated by the m6A RNA quantification kit." (PMID 32676121, 2020). "We further demonstrated that CSN6 facilitates TRIM21 autoubiquitination at the K214 and K217 sites, thereby reducing ubiquitination and degradation of OCT1, a transcription factor for the cancer stemness marker ALDH1A1." (PMID 32225170, 2020). "We characterised the role of CSN6 in regulating cancer stemness, which involves the TRIM21 E3 ubiquitin ligase, transcription factor POU class 2 homeobox 1 (OCT1) and cancer stem cell marker aldehyde dehydrogenase 1 A1 (ALDH1A1)." (PMID 32225170, 2020). "It has been documented that inhibition of ALDH1A1 activity reduces chemotherapy resistance in various cancers such as ovarian and breast cancers." (PMID 32293355, 2020). "And results showed that ALDH1A1 promoted the proliferation, migration and invasion ability of prostate stem cancer cells which indicated that ALDH1A1 was indeed a potential biomarker for prostate stem cancer cells." (PMID 32984354, 2020). "High ALDH1A1 activity is closely related to stemness phenotype of several tumors, possibly contributing to cancer progression and diffusion in the body." (PMID 35582039, 2020). "ALDH1A1 is responsible for the maintenance of the stem-like state in tumor cells, in which several hallmarks of cancer are activated, and it is also frequently overexpressed and/or activated in more differentiated cancer cells." (PMID 35582039, 2020). "Next, they analyzed the differential expression between the silenced and non-silenced cells, where one of the downregulated mRNAs was aldehyde dehydrogenase 1 family member A1 (ALDH1A1), which is a marker of cancer stem cells." (PMID 32650527, 2020). "ALDH1A1 has recently been positively correlated with several in vitro tumor cell behaviors that are surrogates of cancer progression." (PMID 35582039, 2020). "Although many studies have reported that a high expression of ALDH1A1 is associated with tumor progression, this result is controversial as many studies have shown that a high expression of ALDH1A1 is correlated with a favorable prognosis in different cancers." (PMID 32039729, 2020). "The role of ALDH isozyme ALDH1A1 in cancer has been a subject of intensive study, with a number of reports implicating that it is a key factor in maintaining stem cell-like properties in ALDHbr cells while some reports dispute this role." (PMID 32423137, 2020).